HDAC6 (histone deacetylase 6)
Diseases named in the same sentence as HDAC6 in open-access papers (continued):
Sharing a sentence is not in itself a finding about the gene and the disease.
Rett syndrome (4 papers, 2014 to 2021). A severe neurodevelopmental disorder affecting the central nervous system. "HDACs have been suggested as therapeutic targets for Rett Syndrome and HDAC6 inhibition has been linked to improved BDNF trafficking in a Rett mouse model." (PMID 34355696, 2021). "Cellular models using iPSC-derived neurons have also been used to study the role of HDAC6 in Rett syndrome." (PMID 30935091, 2019).
rhabdomyolysis (4 papers, 2018 to 2022). Necrosis or disintegration of skeletal muscle often followed by myoglobinuria. "HDAC6 dysfunction is associated with several pathological conditions in renal disorders, including UUO-induced fibrotic kidneys and rhabdomyolysis-induced nephropathy." (PMID 36552715, 2022). "Other inhibitors of HDAC6, 23BB and F7, also improved the renal function in the cisplatin and the rhabdomyolysis models by reducing apoptosis, decreasing ER stress, and generally suppressing the inflammatory response." (PMID 36076983, 2022). "In our previous studies, we have confirmed that HDAC6 contributed to the pathogenesis of rhabdomyolysis-induced AKI." (PMID 31639165, 2019). "Overall, these data highlighted that 2-methylquinazoline derivative F7 inhibited renal HDAC6 activity and inflammatory responses to protect against rhabdomyolysis-induced AKI." (PMID 31639165, 2019). "In support of our observations, administration of TA, another HDAC6 selective inhibitor, was reported to exert a similar protection in rhabdomyolysis-induced AKI model." (PMID 29632491, 2018). "Overall, these data highlighted that renal protection of novel HDAC6 inhibitor 23BB is substantiated by the reduction of ER stress-mediated apoptosis in tubular epithelial cells of rhabdomyolysis-induced AKI." (PMID 29632491, 2018). "Collectively, these data demonstrated that the selective inhibitory effect of 23BB on HDAC6 activity contributed to ameliorated renal tubular cell apoptosis in rhabdomyolysis-induced AKI." (PMID 29632491, 2018). "The overexpression of HDAC6 was observed in the injured kidneys of rhabdomyolysis-induced AKI." (PMID 31639165, 2019). "To determine whether 23BB may have a renal protective effect by targeting HDAC6, we examined the renal function and pathological changes in a mouse model of rhabdomyolysis-induced AKI." (PMID 29632491, 2018). "Blocking HDAC6 with tubostation A or with compound 23BB significantly improved renal function and alleviated renal tubular injury in AKI models induced by rhabdomyolysis or cisplatin." (PMID 36076983, 2022). "Tubostation A (TA), a specific HDAC6 inhibitor, significantly improved renal function, reduced serum creatinine and blood urea levels, and decreased NGAL expression in rhabdomyolysis-induced AKI." (PMID 36076983, 2022). "We found that the blockage of HDAC6 by 23BB significantly suppressed BAX/BAK and preserved Bcl-2 in the kidney tissues of rhabdomyolysis-induced AKI." (PMID 29632491, 2018). "Recently, several studies demonstrated the increased expression of HDAC6 in cytoplasm of tubular epithelial cells in AKI induced by cisplatin and rhabdomyolysis, among which the elevated production of pro-inflammatory cytokines and apoptosis-related biomarkers were observed." (PMID 31639165, 2019).
skin tumors (4 papers, 2017 to 2025). "Additionally, HDAC6-null mice were more resistant to chemical carcinogen-induced skin tumor formation." (PMID 28052127, 2017). "Our findings demonstrated a generalized upregulation of HDAC5 and HDAC6 genes in HaCaT, HepG2, and A549 after treatment exposure with TRZ, indicating that HDAC5 and HDAC6 are potential lung, liver, and skin cancers therapeutic targets and prognostic biomarkers." (PMID 40077783, 2025). "HDAC6 was previously shown to be required for efficient oncogenic transformation by mutant activated Ras and the absence of HDAC6 slowed the development of DMBA-induced skin tumors." (PMID 29423038, 2018).
type 2 diabetes (4 papers, 2020 to 2023). "In current study, we observed that HDAC6 was markedly activated in the kidneys of type 2 diabetic patients and db/db mice with albuminuria, along with the advanced glycation end products (AGE)‐treated podocytes." (PMID 32885602, 2020).
anaplastic thyroid carcinoma (3 papers, 2019 to 2025). "Considering that HDAC6 deacetylates β-catenin at lysine 49, a site frequently mutated in anaplastic thyroid cancer, the regulation of HDAC6 by PKCα may also influence β-catenin responses in cancer cells." (PMID 39941046, 2025). "A recent study regarding anaplastic thyroid carcinoma was able to restore RHOB promoter activity after using shRNA constructs against HDAC6, effectively showing that HDAC6 does in fact repress the RHOB promoter." (PMID 31200451, 2019).
atopic dermatitis (3 papers, 2021 to 2025). "We studied the role of HDAC6 in atopic dermatitis (AD) and the mechanisms associated with it." (PMID 34588978, 2021). "Although earlier studies have suggested a role for HDAC6 in modulating STAT3 acetylation in allergic dermatitis, the direct relationship between HDACs and FLG expression has remained unclear." (PMID 40730500, 2025). "Additionally, HDAC6 inhibition has been shown to ameliorate inflammatory skin conditions such as atopic dermatitis." (PMID 40807399, 2025). "Several reports have implied the role of HDAC6 in atopic dermatitis (AD) but failed to link this fully, thus, we examined the role of HDAC6 in AD." (PMID 34588978, 2021).
atrial fibrillation (3 papers, 2020 to 2024). A disorder characterized by an electrocardiographic finding of a supraventricular arrhythmia characterized by the replacement of consistent P waves by rapid oscillations or fibrillatory waves that vary in size, shape and timing and are accompanied by an irregular ventricular response. "Decreased levels of acetylatedα-microtubulin in atrial tissue of patients with paroxysmal andpersistent atrial fibrillation coincide with increased histone deacetylase-6(HDAC6) expression and activity." (PMID 39077569, 2023). "However, cardiomyocyte-specific transgenic OE of active HDAC6 with αMHC promoter exacerbated atrial fibrillation and interstitial fibrosis, suggesting a role of HDAC6 catalytic activity in atrial fibrillation." (PMID 38983721, 2024). "Indeed, increased activity of HDAC6 leading to mitochondrial-ER contract site disruption has been reported in atrial fibrillation (AF)." (PMID 32982788, 2020).
Blindness (3 papers, 2017 to 2020). Blindness is the condition of lacking visual perception defined as a profound reduction in visual perception. "Administration of the HDAC6 inhibitor tubastatin A in an inherited blindness zebrafish model resulted in the rescue of retinal morphology and visual function." (PMID 31344897, 2019). "The ability of small molecule HDAC6 inhibitors (TubA, tubacin, ACY-1215 and NF2373) to restore cone photoreceptor vision was evaluated in atp6v0e1–/– zebrafish larvae, a genetic model of blindness potentially relevant to IRD and AMD." (PMID 32984302, 2020).
Burkitt lymphoma (3 papers, 2014 to 2021). A rare form of malignant mature B-cell non-Hodgkin lymphoma. "Burkitt’s lymphoma cells were pharmacologically treated with niltubacin, tubacin or sodium butyrate (NaB) or transfected with siRNAs to knock down the expression of HDAC6." (PMID 25546298, 2014). "Here we sought to identify a role of histone deacetylase 6 (HDAC6) in the metastasis of Burkitt’s lymphoma cells." (PMID 25546298, 2014). "We identified a critical role of HDAC6 in the metastasis of Burkitt’s lymphoma cells, suggesting that pharmacological inhibition of HDAC6 could be a promising strategy for the management of metastatic Burkitt’s lymphoma." (PMID 25546298, 2014). "Suppression of histone deacetylase 6 activity significantly compromised the migration and invasion of Burkitt’s lymphoma cells, without affecting cell proliferation and cell cycle progression." (PMID 25546298, 2014).
calcification (3 papers, 2020 to 2024). Process by which organic tissue becomes hardened by the physiologic deposit of calcium salts. "HDAC6 expression is significantly decreased in aortic valve tissues of patients with aortic stenosis, and its downregulation may promote aortic valve calcification, positioning HDAC6 as a novel target for preventing and treating vascular calcification." (PMID 39125279, 2024).
cerebral infarction (3 papers, 2016 to 2026). An ischemic condition of the brain, producing a persistent focal neurological deficit in the area of distribution of the cerebral arteries. "The association of HDAC6 inhibition with smaller cerebral infarction sizes was upheld in sensitivity analyses incorporating data from studies utilising (i) commercially available HDAC6 inhibitors and (ii) the most widely employed HDAC6 inhibitor (Tubastatin A, 25 mg/kg, Supplements 5 and 6)." (PMID 41549345, 2026). "Meta-analysis demonstrated that animals receiving HDAC6 inhibitors developed significantly smaller cerebral infarctions than controls (standardised mean difference −1.25, 95% confidence intervals: −1.68, −0.81)." (PMID 41549345, 2026). "Meta-analysis including all studies highlighted a strong effect of HDAC6 inhibition in reducing cerebral infarction size (SMD: −1.25; 95% CI: −1.68, −0.81)." (PMID 41549345, 2026). "This proved that HDAC6 increased the area of cerebral infarction." (PMID 31231583, 2019). "Moreover, most identified studies assessed therapeutic efficacy by measuring cerebral infarction size, whereas the impact of HDAC6 inhibition on neurological function was less widely reported and was assessed using varied tests which could not be easily compared." (PMID 41549345, 2026). "In conclusion, available data suggests considerable potential for HDAC6 inhibition to improve outcomes following AIS, evidenced by reductions in the severity of brain infarction and improvements in neurological function, even when treatment is delayed by up to 24 h." (PMID 41549345, 2026).
chronic kidney disease (3 papers, 2018 to 2024). Impairment of the renal function secondary to chronic kidney damage persisting for three or more months. "In addition to that, HDAC6 inhibition attenuated renal tubular injury in chronic kidney disease, evidenced by attenuated proteinuria progression, and diminished tubulointerstitial collagenous matrix deposition." (PMID 39412062, 2024). "In addition, HDAC6 inhibition also exhibits therapeutic effects on chronic kidney disease, heart injury, and spinal cord injury." (PMID 33744850, 2021).
diabetic retinopathy (3 papers, 2020 to 2025). "We investigated the contributing role of the histone deacetylase 6 (HDAC6) to the early stages of diabetic retinopathy (DR)." (PMID 32660051, 2020). "In the same study, specific inhibition of HDAC6 by tubastatin-A exhibited a similar effect in maintaining normal fluid homeostasis in the diabetic retina as observed with TSA, which proposed that HDAC6 inhibition could be a potential therapeutic intervention in diabetic retinopathy." (PMID 34071497, 2021).
endometrial cancer (3 papers, 2020 to 2024). Primary or metastatic malignant neoplasm involving the endometrium (mucous membrane that lines the endometrial cavity). "In summary, the findings exposed in this work indicate that the inhibition of HDAC6 activity is a potential therapeutic strategy for patients suffering from ARID1A‐mutant endometrial cancer diagnosed in advanced stages." (PMID 35167193, 2022). "Here, we show that deficient expression of ARID1A confers increased aggressiveness and metastatic capacity to endometrial cancer cells, while increasing HDAC6 levels." (PMID 35167193, 2022). "Hence, in this scenario, DNA‐damaging agents that induce similar types of DNA breaks should exhibit synergy with HDAC6 inhibitors in ARID1A‐mutated tumours, including endometrial cancer." (PMID 35167193, 2022).
endometriosis (3 papers, 2025). The growth of functional endometrial tissue in anatomic sites outside the uterine body. "Deep infiltrating endometriosis exhibited the highest epithelial (p = 0.032) and stromal (p = 0.007) HDAC6 expression." (PMID 40364006, 2025).
esophageal cancer (3 papers, 2018 to 2024). A primary or metastatic malignant neoplasm involving the esophagus. "However, the expression of HDAC6 in esophageal cancer previously remained unknown." (PMID 30050135, 2018).
esophageal squamous cell carcinoma (3 papers, 2018 to 2025). Esophageal squamous cell carcinoma (ESCC) is a type of esophageal carcinoma (EC) that can affect any part of the esophagus, but is usually located in the upper or middle third. "Overexpressed HDAC6 in oesophageal squamous cell carcinoma (ESCC) is associated with poor prognosis." (PMID 39941046, 2025). "In this study, we found that the high expression of HDAC6 was associated with poor prognosis in esophageal squamous cell carcinoma (ESCC) tissues." (PMID 30050135, 2018). "Another study in esophageal squamous cell carcinoma (ESCC) demonstrated that HDAC6 was the target gene of miR-601, and miR-601 suppressed tumor proliferation and metastasis by down-regulating HDAC6 expression." (PMID 31547835, 2019).
Infertility (3 papers, 2016 to 2025). "Because male CKO mice are infertile, and Hdac6 is an X-linked gene, we selected female CKO mice (i.e., Cyld −/−, Hdac6 +/+) and male Hdac6 KO (HKO) mice (i.e., Cyld +/+, Hdac6 −/Y) for the production of first-generation heterozygous mice." (PMID 27028867, 2016). "Future approaches to address spindle-associated infertility may involve the restoration of spindle function through synthetic mRNA supplementation or pharmacological alteration of acetylation status, such as the use of HDAC6 inhibitors." (PMID 40650169, 2025). "Interestingly, although the sperm flagellar defects induced by loss of Cyld are partially restored in Cyld/Hdac6 DKO mice, these mice remain infertile." (PMID 27028867, 2016). "Given the many negative side effects of chemotherapeutics, e.g., vascular damage, secondary malignancies, infertility, future studies might explore other drug categories to be combined with HDAC6 inhibitors, such as tyrosine kinase inhibitors or other epigenetic blockers." (PMID 36355493, 2022).
invasive breast carcinoma (3 papers, 2015 to 2021). A carcinoma that infiltrates the breast parenchyma. "Moreover, another study documented that enhanced HDAC-6 expression was associated with smaller tumor size and better patients’ survival in invasive breast cancer." (PMID 26502922, 2015).
liver fibrosis (3 papers, 2020 to 2025). "Quantification of HDAC6 staining in 20 individual patient samples revealed a statistically significant increase in F2/F3 compared with F0/F1 samples, this confirming a correlative association between the progression of hepatic fibrosis and elevated hepatic expression of HDAC6." (PMID 40084612, 2025). "This study focuses on the role of histone deacetylases (HDACs) in liver fibrosis, particularly HDAC6." (PMID 40084612, 2025). "This study investigates the potential of HDAC6 as a therapeutic target in liver fibrosis." (PMID 40084612, 2025). "The findings suggest that HDAC6 inhibitors could be promising candidates for treating liver fibrosis and possibly other fibrotic diseases." (PMID 40084612, 2025). "The expression levels of various proteins, specifically PIK3CB, AKT, pAKT, HDAC3, HDAC6, MMP9, MMP2, VIM, and α-SMA, which are implicated in hepatocyte degeneration as well as the initiation and progression of liver fibrosis, were analyzed using Western blotting." (PMID 39683581, 2024). "We synthesized two selective HDAC6 inhibitors, DR‐3 and FDR2, and assessed their effects on hepatic stellate cell (HSC) activation and liver fibrosis using human precision cut liver slices (hPCLS)." (PMID 40084612, 2025). "However, HDAC2, HDAC6, and HDAC8 are notable for their downregulation during the resolution of liver fibrosis, which may indicate a role for these deacetylases in the progression of fibrosis." (PMID 40084612, 2025).
mantle cell lymphoma (3 papers, 2018 to 2023). Mantle cell lymphoma is a rare form of malignant non-Hodgkin lymphoma affecting B lymphocytes in the lymph nodes in a region called the ``mantle zone''. "It is important to know that in this study are included only few cases of follicular lymphoma, mantle cell lymphoma, T-cell lymphoma, and plasmacytomas and the expression pattern of HDAC6 in these histological subgroup remains undetermined." (PMID 30096875, 2018). "For instance, stromal cells residing in the microenvironment of mantle cell lymphoma (MCL) and other non-Hodgkin lymphoma cells downregulate miR-548m in cancer cells, thereupon upregulating its target gene HDAC6." (PMID 37345170, 2023).
myocardial ischemia (3 papers, 2020 to 2025). A disorder of cardiac function caused by insufficient blood flow to the muscle tissue of the heart. "In myocardial ischemia/reperfusion injury in diabetic mice, the inhibition of HDAC6 can reduce myocardial mitochondrial fission by decreasing the level of tumor necrosis factor alpha and recover mitochondrial complex I." (PMID 40377174, 2025).
pancreatic adenocarcinoma (3 papers, 2015 to 2024). "Also, HDAC6 expression was significantly associated with earlier histopathological stages of pancreatic adenocarcinoma." (PMID 39063083, 2024). "In the present study, we determined that HDAC6 is differentially expressed in pan carcinomas, and by survival, we found that HDAC6 was generally associated with the prognosis of pancreatic adenocarcinoma, Thymoma, and uveal melanoma, where low expression of HDAC6 had a significantly worse prognosis." (PMID 34485153, 2021). "Kaplan-Meier survival curves indicated that pancreatic adenocarcinoma patients presenting high HDAC-6 expression had significantly longer survival times compared to those with low expression (log-rank test, p = 0.0113)." (PMID 26502922, 2015). "High HDAC-6 expression was noted in 31 (44.3 %) out of 70 pancreatic adenocarcinoma cases." (PMID 26502922, 2015). "Forty-one (63.1 %) out of 70 pancreatic adenocarcinoma cases were found HDAC-6 positive." (PMID 26502922, 2015). "High HDAC-6 expression was more frequently observed in younger and female pancreatic adenocarcinoma patients, as well as in those with absence of lymph node metastases, at a non significant level though (p = 0.2920, p = 0.2157 and p = 0.1026, respectively)." (PMID 26502922, 2015). "High HDAC-6 expression was more frequently observed in pancreatic adenocarcinoma patients with smaller tumor size and absence of organ metastases, at a non significant level though (p = 0.0864 and p = 0.0663, respectively)." (PMID 26502922, 2015).
pneumonia (3 papers, 2022 to 2024). An acute, acute and chronic, or chronic inflammation focally or diffusely affecting the lung parenchyma, caused by an infection in one or both of the lungs (by bacteria, viruses, fungi, or mycoplasma.). "The combination of ACY-241 with nivolumab (anti-PD-L1 antibody) was shown to cause side effects such as dyspenia (1/17) and pneumonia (2/17) in patients with NSCLCs who had not received an HDAC6 inhibitor or immune checkpoint inhibitor (n = 17)." (PMID 36076996, 2022).